CYBRD1 (cytochrome b reductase 1)
Diseases named in the same sentence as CYBRD1 in open-access papers (continued):
Sharing a sentence is not in itself a finding about the gene and the disease.
myelodysplastic syndrome (1 paper, 2021). A clonal hematopoietic disorder characterized by dysplasia and ineffective hematopoiesis in one or more of the hematopoietic cell lines. "A study of immune infiltration in patients with myelodysplastic syndrome with advanced clinical pathological features found that CYBRD1 expression regulates the cell cycle and DNA repair, whereas CD34 is downregulated and triggers an immune response." (PMID 34594380, 2021).
pancreatic cancer (1 paper, 2017). "Furthermore, NOSTRIN was found to be a potential negative regulator of disease aggressiveness in pancreatic cancer and CYBRD1 was identified as part of an iron regulatory gene signature that predicts outcome in BC." (PMID 28122328, 2017).
urothelial carcinoma (1 paper, 2021). A malignant neoplasm derived from the transitional epithelium of the urinary tract (urinary bladder, ureter, urethra, or renal pelvis). "The results demonstrated low expression of PDE5A, RECK, ZEB2, and CYBRD1 in urothelial carcinoma tissue." (PMID 33987019, 2021). "PDE5A, RECK, ZEB2, and CYBRD1 play essential roles by interacting with other miRNAs and genes in urothelial carcinoma networks which are represented by purple circles." (PMID 33987019, 2021).
cancer (10 papers, 2017 to 2024). A tumor composed of atypical neoplastic, often pleomorphic cells that invade other tissues. "Cancer cells exhibit an enhanced requirement for iron compared to normal cells; thus, CYBRD1 has been reported to play a critical role in carcinogenesis." (PMID 34326882, 2021). "Several iron-related genes, such as scavenger receptor class A member 5 (SCARA5), erythroferrone (ERFE), lipocalin 2, TfR2, SLC11A1, and cytochrome B reductase 1 (CYBRD1), were found to be dysregulated in different cancers, likely due to abnormal DNA methylation." (PMID 39595619, 2024). "Similar to GNG12, most of the existing researches focusing on this gene are related to cancers, and the knowledge regarding the role of CYBRD1 in MS remains unclear." (PMID 35281467, 2022). "Conclusively, CYBRD1 upregulation has been reported in several cancers." (PMID 34326882, 2021). "Although the potential of CYBRD1 as a biomarker has been suggested, its specific effects on cancer cell aggressiveness remain unclear as of yet." (PMID 34326882, 2021). "Moreover, CYBRD1 may serve as a prognostic marker for various cancers." (PMID 34594380, 2021).
tumor (9 papers, 2017 to 2025). "The expression of CYBRD1 and primary therapy outcome and tumor residual were significantly associated with shorter survival." (PMID 34594380, 2021). "CYBRD1 encodes an iron-regulated ferric reductase, and altered expression may modulate immune responses by affecting iron metabolism, ferroptosis (iron-dependent cell death), and the tumor microenvironment." (PMID 40918096, 2025). "IFN-α treatment decreased the xenograft tumor weight and volume in mice, whereas CYBRD1 overexpression attenuated the inhibitory effects of IFN-α on xenograft tumor growth." (PMID 34326882, 2021). "Intratumor injection with IFN-α or CYBRD1 overexpression lentivirus was performed after xenograft tumor appeared." (PMID 34326882, 2021). "Patients with high levels of CYBRD1 expression were prone to the development of a poorly differentiated tumor and experience of an unfavorable outcome." (PMID 34594380, 2021). "The results showed that CYBRD1 expression significantly enhanced in advanced stage (P=0.014), lymphatic invasion (P=0.017), and poor-differentiated tumor (P < 0.001)." (PMID 34594380, 2021). "IHC was applied to measure the expression of CYBRD1 in OV tissues and verified CYBRD1 located within tumor cells and enriched predominantly in the cytoplasm of tumor cells." (PMID 34594380, 2021). "We speculated whether the upregulation of CYBRD1 expression could promote tumor progression through immune-related pathways." (PMID 34594380, 2021). "Furthermore, we verified that CYBRD1 was upregulated in OV and significant correlated with lymph nodes metastasis, advanced stage, poor-differentiated tumor, and poor clinical prognosis in East Hospital cohort." (PMID 34594380, 2021). "The expression of the negative genes (ELOVL5, PTGER3, KIAA1324, and CYBRD1) in tumors was lower than that in normal and tumor-adjacent tissues." (PMID 36341435, 2022). "Additionally, CYBRD1 inhibited activation of focal adhesion kinase which is crucial for tumor adhesion and metastasis and this effect was independent of cellular iron signaling pathways." (PMID 37632052, 2023).
CYBRD1 also shares sentences with these, for which no sentence is quoted: adenocarcinoma (2 papers); African trypanosomiasis (1); asthma (1); Barrett's metaplasia (1); celiac disease (1); ductal carcinoma (1); duodenal cancer (1); endometrial cancer (1); esophageal carcinoma (1); hepatocellular carcinoma (1); invasive ductal carcinoma (1); metastasis (1); Ovarian Tumor (1); prostate carcinoma (1); rheumatoid arthritis (1).